BCL2 (BCL2 apoptosis regulator)
Diseases named in the same sentence as BCL2 in open-access papers (continued):
Sharing a sentence is not in itself a finding about the gene and the disease.
tumor (continued). "In this way, LMTK3 acts as a tumour suppressor that regulates cell apoptosis, modulating the level of anti-apoptotic Bcl-2 and decreasing pro-apoptotic Bax and caspase-3." (PMID 34064250, 2021). "In contrast to the dependency observed during transformation, we have shown that tumor-derived CSCs are solely BCL-XL-dependent, pointing to a loss of the initial BCL-2 dependence." (PMID 34117376, 2021). "Subsequently, we found that combination treatment had a better effect on reducing the phosphorylation of the STAT3/Bcl-2 pathway via western blottings on xenograft tumor tissues." (PMID 34611143, 2021). "Using cutoff values of 50% positive tumor cells for BCL-2 and BCL-6, 92 (31.60%) cases were positive for BCL-2, and 93 (31.90%) cases were positive for BCL-6." (PMID 35127536, 2021). "Inversely, tumor suppressors such as Beclin-1 prevent inhibition of IP3R-mediated Ca2+ ion release into the mitochondria partly by interacting with Bcl2 which then dissociates from IP3R, thereby restoring the ER-mitochondrial Ca2+ ion transfer." (PMID 34572262, 2021). "While group IV showed a highly significant increased expression of Bcl-2 only on 20 days from the onset of tumor formation as compared to both groups I and II (P<0.001)." (PMID 33773560, 2021). "The mRNA levels of BCL9 and BCL2 were found to be upregulated in the tumor tissues compared with adjacent normal tissues." (PMID 33838016, 2021). "The first BH3-mimetic with high anti-tumor activity was the dual BCL-2/BCL-XL inhibitor ABT-737, whose diminished efficacy observed in MM cells when co-cultured with BM-MSCs was partially reverted by IL6 blockage." (PMID 33806619, 2021). "Venetoclax is a selective small-molecule BCL2 inhibitor that can induce apoptosis in tumor cells that are dependent on BCL2 for survival." (PMID 34068316, 2021). "Histological features were evaluated and revealed a highly cellular tumor with positive expression of BCL2, CD34, CD99, and STAT6 proteins that are consistent with a diagnosis of SFT." (PMID 34765368, 2021). "After tumor sphere-forming in CD44+/CD133+ pancreatic cells, high levels of Notch/Bcl-2 and loss of miR-34 have been identified." (PMID 34094034, 2021). "The results of Western blot analysis showed that, compared with unloaded or NC mimic-loaded exosomes, miRNA-129-5p-loaded exosomes reduced Bcl-2 expression and increased the expression of Bax in tumor cells." (PMID 34775889, 2021). "We found tumor tissues with high FAM83B expression had high BCL2 and CCND1 expression, and had low apoptosis inhibitor XIAP expression." (PMID 33423038, 2021). "Downregulation of these miRNAs promotes overexpression of several oncogenes including BCL2 (BCL2 apoptosis regulator), inhibiting apoptosis of tumor cells and enhancing cell proliferation." (PMID 34440837, 2021). "Butyrate-induced expression of numerous pro-apoptotic genes, such as Bax and Bak, and suppression of anti-apoptotic genes such as Bcl-2, lead to induction of the caspase cascade in tumor cells." (PMID 34359944, 2021). "miR-15a and miR-16 act as tumor suppressors: they downregulate multiple oncogenes (BCL2, MCL1, CCND1, and WNT3A), decreasing PC cell survival, proliferation, invasion, and EMT by targeting TGF-β signaling." (PMID 34830196, 2021). "Both CASP3 and BCL2 were apoptosis-related proteins, which inhibited tumor growth by regulating and inducing cancer cell apoptosis." (PMID 34773055, 2021).
tumor (continued). "Independent confirmation with a single-cell RNA sequencing dataset of normal and CRC tumor samples revealed a significant decrease in BCL-2 and concomitant increase in BCL-XL, specifically in the epithelial tumor compartment." (PMID 34117376, 2021). "The correlation between high expression of BCL2 protein and sensitivity also appears to hold for other neoplasms, but this relationship can be lost when high levels of venetoclax-insensitive BCL2 paralogs such as MCL1 are expressed." (PMID 33796823, 2021). "In further analysis, we established cells with different Beclin-1 and Bcl-2 expression states using plasmid vectors and siRNA before making in vitro observations of the invasiveness of tumor cells." (PMID 34257544, 2021). "High expression of caspase-3, caspase-8, and Bax, and low expression of Bcl-2 in tumor cells after treatment with amniotic mesenchymal cells confirmed the apoptosis as the main mechanism of cancer cell death." (PMID 33579346, 2021). "Mice models of pancreatic cancer presented a significant reduction of tumor volume, suppression of NF-κB regulated genes (for cyclin D1, Bcl-2, BclxL, COX-2, matrix metalloproteinases, VEGF), and decreased microvessel density." (PMID 35010907, 2021). "In turn, the combination with chemotherapy or ionizing radiation can increase sensitivity to BCL‐2 inhibitors in preclinical tumor cell lines and patient samples by a reduction in MCL‐1 levels." (PMID 33347715, 2021). "Bax and Bcl-2 are the major members of the Bcl-2 family and play a key role in tumor progression or inhibition of the intrinsic apoptotic pathway triggered by mitochondrial dysfunction." (PMID 33430854, 2021). "The decreased Bcl2 expression detected in the current study shows the action of CPT-11's antineoplastic effects by stimulating tumor cell apoptosis." (PMID 34630855, 2021). "They proved that both Bcl-xL monospecific oligonucleotide and Bcl-xL/Bcl-2 bispecific oligonucleotide effectively reduced tumor cell viability by induction of apoptosis." (PMID 33803452, 2021). "IHC showed that the tumour tissues of the HIF1α-ko or HIF2α-ko individual group had lower expression of Ki67 and Bcl2 than the control and the dual HIF1α and HIF2α knockout group." (PMID 33986256, 2021). "In the mitochondria, PKM2 interacts with Bcl2 and phosphorylates it at threonine (T) 69, thus preventing Cul3-RBX1 ligase-mediated degradation of Bcl2, ultimately enhancing apoptosis resistance of tumour cells." (PMID 34759927, 2021). "In tumor cells, Bcl-2 interacts with COX5a, which results in the alteration of mitochondrial respiration under oxidative stress." (PMID 34685389, 2021). "Considering the key role of apoptosis in GB progression, we evaluated the pro-apoptotic Bax, and anti-apoptotic Bcl2 protein by western blot analysis on tumor samples." (PMID 34298658, 2021). "Transfection of smac sensitizes tumor cells to drug-induced apoptosis by enhancement of mitochondrial Bax accumulation and inhibition of Bcl-2-mediated anti-apoptotic activity." (PMID 34617137, 2021). "In particular, we minimize tumour volume and maximize the apoptotic potential by minimizing the Bcl-2 concentration and maximizing the BAX level while minimizing total injection amount of both IFN-β and JAK2 inhibitors (DDP)." (PMID 34631119, 2021). "Treatment with EQ had evident anti-tumor effects on EAC as revealed by the remarkable decrease in the expression of the anti-apoptotic gene Bcl-2 and by a significant increase in the expression of apoptotic genes (BAX and caspase-3)." (PMID 34829755, 2021). "The BCL2 gene was found to be aberrantly overexpressed in a wide range of human tumours, including B-cell and T-cell lymphomas, breast, lung, prostate, cervical and colorectal cancers as well as gliomas, melanomas and neuroplastomas." (PMID 33638996, 2021). "Further, tumor cells harvested from the MJ group displayed a significantly declined Hsp70, Bcl-2, and TERT expression." (PMID 33718176, 2021).
tumor (continued). "A significant association was found for both SOX2 and Bcl-2 overexpression with TNM staging (p = 0.02, p = 0.04) and tumor grading (p = 0.01, p = 0.003), respectively." (PMID 34436030, 2021). "Furthermore, miR-34a encapsulated in chitosan/PLGA nanoparticles inhibited tumor growth in murine xenograft models of human multiple myeloma disease since this miRNA directly downregulates proteins associated with tumor development, i.e., Bcl-2, Notch 1, and CDK6." (PMID 35011442, 2021). "AZD0466 exhibits potent and dose dependent anti-tumour efficacy as a single agent in the Bcl-2 dependent RS4;11 subcutaneous model." (PMID 33495510, 2021). "spiralis group, Bcl-2 expression 20 days from the onset of tumor formation was higher than that of 30 and 40 days which indicates that T. spiralis apoptotic effect on HCC had increased with time." (PMID 33773560, 2021). "Bcl2, an antiapoptotic protein found in mitochondria, plays an important role in determining the occurrence of apoptosis and regulating tumor progression." (PMID 34630074, 2021). "Subsequently, we examined the expression of anti-apoptotic protein BCL2, which have been reported to be up-regulated by β-catenin signals in tumor cells." (PMID 34319913, 2021). "Overexpression and continuous activation of STAT3 can upregulate the anti-apoptotic protein (Bcl-2) to inhibit the apoptosis of tumor cells and prolong the cell life cycle." (PMID 34493692, 2021). "These Treg cells in Cd300afl/fl;ItgaxCre mice showed higher expression of Ki67 and CTLA-4 than did Cd300afl/fl mice, although the expressions of CD25, GITR, and BCL2 on tumor-infiltrating Treg cells were comparable between two genotypes of mice." (PMID 34751648, 2021). "The results showed that the expression of Bcl-2 in tumor tissues of miR-449a Exo group mice was significantly lower than that of the other three groups, P < 0.01." (PMID 34521413, 2021). "Because of the fundamental function of Bcl-2 in the regulation of apoptosis, the Bcl-2 protein is a potent target for the development of novel anti-tumor treatments." (PMID 34638779, 2021). "Such molecules as p-Akt, p-mTOR, p-p38, MMP-2/9, and BCL-2 were all downregulated, whereas Bax and cleaved-caspases-9 were upregulated after fucoxanthin treatment of the tumor tissues." (PMID 34440090, 2021). "Among them, VEGF and bFGF apply their anti-apoptotic effects by enhancing BCL-2 expression and increasing the BCL-2/Bax ratio in tumor cells." (PMID 33579346, 2021). "Autophagy was also noted in tumours treated with nanoliposomes-Bcl-2 siRNA, indicated by enhanced expression of autophagy markers (LC-3II and ATG5)." (PMID 34575883, 2021). "Previously, we had identified and characterized a novel BCL2 inhibitor, Disarib, with the potential to eliminate tumor cells in a BCL2 specific manner leading to reduction in tumor burden in multiple mouse models." (PMID 33976278, 2021). "Some studies have also found that drug-induced tumor cell death is related to the Bcl-2–Beclin 1 complex pathway." (PMID 34830185, 2021). "The realization of the goal is exemplified by delivering Bcl-2 siRNA and a tumor-resistant Cu complex to cancer cells with an ATP-responsive nanocarrier." (PMID 34163720, 2021). "The Beclin1 protein contains Bcl-2 homology-3 (BH3) domain which interacts with BH3 receptor domain of antiapoptotic proteins like Bcl-2 and Bcl-xL and inhibits Beclin1 autophagic activity as well as its tumor suppressor activity." (PMID 33628386, 2021). "Tumor hypoxia has been demonstrated to increase the expression of anti-apoptotic Bcl-2 and Bcl-xL and decrease pro-apoptotic Bcl-2 such as Bax, Bad and Bid." (PMID 33708620, 2021).
tumor (continued). "Subsequently, we performed the mRNA and protein detection of proliferation markers (CYCLIN B1, PCNA, and KI-67) and apoptosis markers (BAX and BCL2) in the tumor tissues of each mice group." (PMID 34447747, 2021). "Since cancer cells exploit Bcl-2 to evade apoptosis, it appears that in many tumours there is a selection of Bcl-2-dependent cells." (PMID 34439105, 2021). "The expression of the BCL-2 gene in FaDu tumor cells was less affected by combined treatment with CisPt + RSV (p < 0.04, *), compared to the effect induced by RSV alone." (PMID 34204834, 2021). "Our results showed the combination therapy increased BAX/BCL2 ratio in both tumor and normal cell lines than CAP or CUR treatments." (PMID 34825002, 2021). "Mitochondrial anti-apoptotic Bcl2 and BclxL proteins, are overexpressed in multiple tumour types, and has been involved in the progression and survival of malignant cells." (PMID 33345633, 2021). "In preclinical ALL models, the anti-tumor activity of BCL-2 inhibitors, including venetoclax and navitoclax, was shown." (PMID 34575992, 2021). "Compared with the control, we found that the expression of extrinsic protein TNF-α increased and the expression of internal protein Bcl-2 decreased in ICT-treated tumor tissues." (PMID 33460401, 2021). "BCL-2 is another gene responsible for inhibiting apoptosis and promoting aberrant cell proliferation, so we analyzed how its expression was modulated in tumor cells treated with RSV + CisPt." (PMID 34204834, 2021). "Ag-BB was also found to stimulate apoptotic cascade expression in tumor cells through downregulating of anti-apoptotic protein (Bcl-2) expression and upregulating the mRNA expression of pro-apoptotic proteins (Bax and caspase-3)." (PMID 34771481, 2021). "For conclusive statement regarding correlation of bcl-2 expression with grade of the tumor requires more and larger studies." (PMID 34178320, 2021). "Bcl-2 is a key anti-apoptosis pathway of cancer cells and the nonlinear V-shaped dose response led to a bell-shaped curve of anti-tumor efficacy." (PMID 34669701, 2021). "Analyzing tumor tissue lysates by western blots demonstrated that BRD4-regulate proteins (Bcl-2, Myc, cyclin D1) were significantly downregulated in I-BET726-treated A431 tumor tissues." (PMID 32371868, 2020). "In mice, fruti prevented tumor development and reduced Cyclin D1, Bcl-2 and Rela gene levels, and reduced the p-NF-κB/NF-κB ratio in tumor tissue." (PMID 33020521, 2020). "Our findings suggest that SLN-DTX inhibits tumor growth and prevents lung metastasis by reducing the production of IL-6 serum level, inducing apoptosis of the tumor cells and reduction of tumor cell proliferation and BCL-2 expression." (PMID 32164731, 2020). "The ratio of Bax (apoptotic protein) and Bcl-2 (anti-apoptotic protein) can precisely regulate tumor cell apoptosis." (PMID 33585454, 2020). "Both venetoclax and S63845 exerted selective cytotoxicity against the tumor cells which highly expressed Bcl-2 or Mcl-1 protein, but had limited efficacy in tumor cells with low expression of Bcl-2 or Mcl-1 consistent with previous studies." (PMID 33362794, 2020). "FACS technology now allows BH3 profiling to be performed in polyclonal cell populations, potentially providing insight into BCL-2 dependency despite tumor heterogeneity." (PMID 32131385, 2020). "The results indicated that paxillin promoted Bcl-2 activation by mediating ERK activation, which was associated with tumor formation efficacy in mice." (PMID 32849902, 2020). "Within these treatments, the combination with TNuF and RT provided the most effective modulation to tumor Bcl-2 mRNA." (PMID 32872195, 2020).
tumor (continued). "In tumor tissue of animals treated with fruti we observed a reduction of Cyclin D1, Bcl-2 and Rela (a protein from NF-κB pathway) expression and of p-NF-κB/NF-κB protein ratio, in line with our observations from in vitro experiments." (PMID 33020521, 2020). "Bcl-2 markedly decreased, leading to a dramatic increase in the Bax/Bcl-2 ratio in LAIR-1 overexpression tumor samples, while the expression levels of ki-67 and PCNA remained unchanged." (PMID 32628130, 2020). "Age, gender, IDH1 status, Bcl2 and Ki67 mean scores and labelling indices revealed significant statistical differences among tumor grades." (PMID 32856872, 2020). "The expression levels of proteins related to apoptotic cell death, including Bcl-2, Bax, cleaved caspase-3, and cleaved caspase-9 in the tumor tissues was also consistent with the results in vitro." (PMID 32606352, 2020). "In the in vivo experiment, the data showed that ZYHT can downregulate the protein expression of PI3K, AKT, CyclinD1, and Bcl-2 in the subcutaneous xenograft GC tumor tissues." (PMID 32382534, 2020). "Immunohistochemistry revealed that LC3-B and Bax expression was strongly increased in xenograft tumor tissues, whereas Bcl-2 expression was obviously decreased after treatment." (PMID 31901897, 2020). "It has been reported in the literature that AKT and STAT3 have also been identified to be involved in the regulation of downstream factors, including PCNA, Bcl2 and CyclinD1, and to manage tumor proliferation and apoptosis." (PMID 32463472, 2020). "We confirmed that epalrestat promoted HCC apoptosis through regulating the Bcl-2/caspase-3 pathway, thus enhancing sorafenib anti-tumour effects." (PMID 32547320, 2020). "For example, a recent study has found that resveratrol is a tumor suppressor compound in grapes that induces apoptosis through a mitochondrial pathway regulated by Bcl-2." (PMID 32104190, 2020). "Tumor-infiltrating CD8+ T cells were also characterized by a significant upregulation in the expression of Bcl-2 in comparison to control mice, indicative of increased survival." (PMID 32461349, 2020). "The accumulation of miR-494 within the cells, as a consequence of the reduced release, suppressed tumor growth and metastasis, increasing Bcl2 expression." (PMID 31952362, 2020). "Studies have shown that a low Bax/Bcl-2 ratio can favor tumor survival as well as impart resistance to various kinds of cell death stimuli including genotoxic, radiation or hypoxia." (PMID 32984059, 2020). "Using western blot, we determined the expression of cleaved caspase 3 and Bcl-2 to evaluate apoptosis in tumor cells." (PMID 32636744, 2020). "Previous studies have demonstrated an abundant expression of anti-apoptotic proteins, commonly BCL-2, BCL-XL, and BCL-W in multiple myeloma cell lines and non-SCLC tissues which are associated with tumor advancement, sustenance and chemoresistance." (PMID 33381025, 2020). "The synergy between DNA damage and BCL-2 inhibition in MCPyV-positive cell lines provides an explanation for why downregulation of BCL-2 mRNA alone was insufficient to impede tumor growth in patients with metastatic or regionally recurrent MCC." (PMID 32093022, 2020). "In most tumors, Bcl‐2 expression levels are elevated, while Bax expression levels are reduced, which leads to an increase in the amount of Bcl‐2/Bax heterodimers and Bcl‐2 homodimers, thereby inhibiting tumor cell death." (PMID 32750218, 2020). "As main findings, nano-complex revealed to be a significant agent to reduce tumor diameter by inducing bax and caspase activity and declining the expression of akt and bcl2 genes in tumor microenvironment, involved in apoptosis upregulation." (PMID 33521059, 2020). "Although knockdown of BCL-XL and BCL-2 improved the cytotoxic activity of S63845 and its combination with navitoclax increased the anti-tumor cytotoxicity, the therapeutic range of S63845 with navitoclax was narrow in in vivo studies." (PMID 32152266, 2020).